SLC16A4 (solute carrier family 16 member 4)
Description:
Probable monocarboxylate transporter.
Synonyms: MCT4; MCT5
Tractability: Antibody: its Gene Ontology location is reachable by antibodies, with high confidence; UniProt places it where antibodies can reach, with medium confidence; UniProt predicts a signal peptide or a membrane-spanning region. PROTAC: ubiquitination databases record sites on it.
Gene: Protein-coding gene on chromosome 1 (110,362,848 to 110,391,082, reverse strand). Ensembl gene ENSG00000168679.
Subcellular location: Cell membrane
Subcellular location (Human Protein Atlas): Cytosol; Microtubules; Cytokinetic bridge
Gene Ontology:
Molecular function: monocarboxylic acid transmembrane transporter activity; transmembrane transporter activity
Biological process: carboxylic acid transmembrane transport; monocarboxylic acid transport; transmembrane transport
Cellular component: membrane; plasma membrane
Genetic constraint (gnomAD): Loss-of-function variants: 39 observed, 46.86 expected, observed/expected ratio (o/e) 0.83, 90% interval 0.64 to 1.09. The upper end of that interval is the gene's LOEUF score, 1.09, which puts it in group 4 of 6, group 1 being the genes least tolerant of losing a copy. Missense variants: 487 observed, 555.19 expected, observed/expected ratio (o/e) 0.88, 90% interval 0.81 to 0.94. Synonymous variants: 171 observed, 194.84 expected, observed/expected ratio (o/e) 0.88, 90% interval 0.77 to 1.
Homologues: Orthologues: chimpanzee SLC16A4 (99% identical), macaque SLC16A4 (97% identical), rabbit SLC16A4 (86% identical), guinea pig SLC16A4 (83% identical), mouse Slc16a4 (83% identical), dog SLC16A4 (80% identical), pig SLC16A4 (80% identical), rat Slc16a4 (77% identical), zebrafish slc16a4 (51% identical), Drosophila melanogaster CG13907 (26% identical), Drosophila melanogaster Mct1 (26% identical), Caenorhabditis elegans mct-6 (26% identical), and 10 more. Paralogues in human: SLC16A12 (26% identical), SLC16A6 (25% identical), SLC16A7 (24% identical), SLC16A9 (24% identical), SLC16A14 (24% identical), SLC16A13 (23% identical), SLC16A11 (23% identical), SLC16A5 (23% identical), SLC16A3 (22% identical), SLC16A1 (22% identical), SLC16A8 (22% identical), SLC16A10 (19% identical), and 1 more.
Diseases named in the same sentence as SLC16A4 in open-access papers:
SLC16A4 is named in the same sentence as 13 diseases in open-access papers, as found by Europe PMC text mining. Sharing a sentence is not in itself a finding about the gene and the disease. The quoted sentences say what the papers report.
lung carcinoma (2 papers, 2024 to 2025). "In conclusion, this study not only established an efficient diagnostic model for lung cancer but also identified SLC16A4 as a promising biomarker with potential applications in early diagnosis and immunotherapy." (PMID 40867526, 2025). "Using lung cancer datasets from The Cancer Genome Atlas (TCGA), we investigated the association between SLC16A4 expression and tumor stemness, tumor mutation burden (TMB), as well as microsatellite instability (MSI)." (PMID 40867526, 2025). "Finally, Kaplan–Meier survival analysis using the KMPlotter online tool indicated that low expression of SLC16A4 was associated with poorer overall survival in lung cancer patients, highlighting its potential as a prognostic biomarker." (PMID 40867526, 2025). "In this study, we established a lung cancer diagnostic model based on serum proteomic data using four machine learning algorithms (nnet, glmnet, sgboost, and svm) and further analyzed the role of the key protein SLC16A4 in lung cancer." (PMID 40867526, 2025). "Furthermore, we investigated the potential mechanisms underlying the downregulation of SLC16A4 in lung cancer using multi-omics data from TCGA." (PMID 40867526, 2025). "Moreover, the expression of SLC16A4 was closely associated with the clinical pathological features of lung cancer patients, including gender, tumor invasion depth, lymph node metastasis, tumor stage, and smoking history." (PMID 40867526, 2025). "After grouping based on different clinical characteristics, we found that SLC16A4 expression was significantly associated with gender, tumor invasion depth (M), lymph node metastasis (N), distant metastasis (T), tumor stage, and smoking history in lung cancer patients." (PMID 40867526, 2025). "Upregulation of MCT4 (also known as solute carrier family 16 member 4 or SLC16A4), a major lactate transporter, contributes to the immunosuppressive phenotype including M2 macrophage polarization and T cell hypofunction observed in a Lkb1-deficient Kras-driven lung cancer mouse model." (PMID 39544365, 2024). "EdU assays further validated that overexpression of SLC16A4 significantly inhibited lung cancer cell proliferation." (PMID 40867526, 2025). "In the TCGA lung cancer dataset, SLC16A4 expression was significantly positively correlated with the expression of several immune checkpoint genes." (PMID 40867526, 2025). "Through in-depth research into the biological functions of SLC16A4, it is expected to provide new insights for early lung cancer diagnosis and personalized treatment in the future." (PMID 40867526, 2025). "Further analysis was performed to investigate the correlation between SLC16A4 expression and clinical pathological features using the TCGA lung cancer dataset." (PMID 40867526, 2025). "We further explored the potential biological significance of SLC16A4 in lung cancer using Gene Set Enrichment Analysis (GSEA)." (PMID 40867526, 2025). "Upon treatment with the methylation inhibitor 5-aza to suppress DNA methylation, the expression of SLC16A4 was significantly upregulated in the lung cancer cell lines H1299 and A549." (PMID 40867526, 2025). "β-galactosidase staining indicated that overexpression of SLC16A4 promoted cell senescence in lung cancer cells." (PMID 40867526, 2025). "We further analyzed the correlation between SLC16A4 expression and the expression of immune checkpoint genes in lung cancer." (PMID 40867526, 2025). "CCK-8 assays showed that overexpression of SLC16A4 significantly reduced the proliferative capacity of lung cancer cells A549 and H1299." (PMID 40867526, 2025). "We further analyzed the relationship between SLC16A4 expression and immune cell infiltration in lung cancer." (PMID 40867526, 2025). "To further validate this relationship, we overexpressed SLC16A4 in lung cancer cell lines, A549 and H1299, and observed a marked reduction in SOX2 expression, as assessed by qPCR." (PMID 40867526, 2025).
lung carcinoma (continued). "Our study found that the expression of SLC16A4 at both the mRNA and protein levels was significantly lower in lung cancer tissues compared to normal tissues." (PMID 40867526, 2025). "Due to the upregulation of the candidate biomarker XAGE1A in lung cancer tissues, which is inconsistent with its downregulated expression in plasma, we initially chose another candidate biomarker SLC16A4 for further analysis." (PMID 40867526, 2025). "SLC16A4 mRNA expression was significantly lower in lung cancer samples than in normal tissues in the TCGA LUAD and LUSC datasets." (PMID 40867526, 2025). "Our analysis identified SLC16A4 as a key protein in the model, which was significantly downregulated in lung cancer serum samples compared to normal controls." (PMID 40867526, 2025). "Using the Oncopredict package, we calculated the drug sensitivity scores for the TCGA lung cancer samples and further evaluated the correlation between SLC16A4 expression and drug sensitivity." (PMID 40867526, 2025). "Functional assays revealed that overexpression of SLC16A4 significantly inhibited lung cancer cell proliferation and induced cellular senescence, suggesting its potential role in lung cancer development." (PMID 40867526, 2025). "In vitro experiments revealed that overexpression of SLC16A4 significantly inhibited the proliferation of A549 and H1299 lung cancer cells and promoted cellular senescence." (PMID 40867526, 2025). "We investigated the effects of SLC16A4 on lung cancer cell proliferation and senescence." (PMID 40867526, 2025). "Notably, SLC16A4 expression in male lung cancer tissues was significantly lower than in female lung cancer tissues (p < 0.001)." (PMID 40867526, 2025). "Based on multi-omics data from the TCGA database, we further discovered that the low expression of SLC16A4 in lung cancer may be regulated by DNA copy number variations and DNA methylation." (PMID 40867526, 2025). "In addition, analysis of multiple lung cancer datasets in the GEO database confirmed the consistent downregulation of SLC16A4 mRNA in lung cancer tissues across various cohorts." (PMID 40867526, 2025). "The key protein SLC16A4 in the model not only serves as a potential biomarker for lung cancer but may also play an important role in lung cancer immunotherapy and targeted therapy." (PMID 40867526, 2025). "Moreover, qPCR analysis revealed that overexpression of SLC16A4 upregulated the expression levels of CDKN1A and CDKN2A in A549 and H1299 cells, suggesting that SLC16A4 may suppress lung cancer cell proliferation by regulating the cell cycle." (PMID 40867526, 2025). "Correlation analysis further showed that the expression of SLC16A4 was associated with the infiltration of various immune cells, suggesting that SLC16A4 might participate in the occurrence and development of lung cancer by regulating immune responses in the tumor microenvironment." (PMID 40867526, 2025). "In relation to smoking history, lung cancer tissues from never-smokers and patients who had quit smoking for more than 15 years exhibited higher SLC16A4 expression than those from current smokers and individuals who had quit smoking for less than 15 years." (PMID 40867526, 2025). "Furthermore, protein expression levels of SLC16A4 in the CPTAC LUAD and LUSC datasets were also significantly lower in lung cancer tissues compared to normal tissues." (PMID 40867526, 2025).
prostate carcinoma (2 papers, 2019 to 2021). A carcinoma that arises from epithelial cells of the prostate gland. "In Pereira’s study, to maintain a high glycolytic phenotype, prostate cancer is effectively transported to the breast via SLC16A1 and SLC16A4.The expression level of SLC16A1 in metastatic prostate cancer cells is significantly higher than that in more restricted prostate cancer cell lines." (PMID 34631536, 2021).
colon cancer (1 paper, 2015). "We thus compared with the same gene expressions (up-regulated transcripts: SLC16A4, DSC3, ALDOB, EPHX4, ARHGAP24; and down-regulated transcripts (MS4A12, TMIGD1, CASP5) in 5 colon cancer lines: HCT 116, Caco2, HT-29, Lovo, and C32." (PMID 25929336, 2015).
colorectal tumors (1 paper, 2015). "Highly elevated SLC16A4 expression appears to be PMP specific, with equivalent elevated levels limited to only some colorectal tumors and cancer cell lines." (PMID 25929336, 2015). "Thus, up-regulated expression was greater in PMP for SLC16A4, DSC3, ALDOB compared with colorectal tumors." (PMID 25929336, 2015).
lung adenocarcinoma (1 paper, 2025). A carcinoma that arises from the lung and is characterized by the presence of malignant glandular epithelial cells. "In both the TCGA lung adenocarcinoma and squamous cell carcinoma cohorts, SLC16A4 exhibited frequent copy number deletions, particularly single-copy deletions." (PMID 40867526, 2025).
lymph node metastasis (1 paper, 2025). "The expression of SLC16A4 was closely associated with clinical pathological features such as gender, tumor stage, lymph node metastasis, and smoking history." (PMID 40867526, 2025).
pancreatic cancer (1 paper, 2020). "The boxplot of the RNA-Seq expression in 179 pancreatic cancer vs 171 normal pancreas samples demonstrated that SLC16A1, SLC16A2, SLC16A3, SLC16A4, SLC16A5 and SLC16A13 were increased with statistical meaning." (PMID 32355273, 2020). "In detail, in pancreatic cancer, the SLC16A1 and SLC16A4 mRNA expression levels increased in all 3 cases." (PMID 32355273, 2020).
pulmonary fibrosis (1 paper, 2026). Chronic progressive interstitial lung disorder characterized by the replacement of the lung tissue by connective tissue, leading to progressive dyspnea, respiratory failure, or right heart failure. "Given the pivotal role of SLC16A4 and its regulation of lactate metabolism in COVID‐19‐associated pulmonary fibrosis, targeting this pathway presents promising therapeutic potential." (PMID 41532065, 2026). "Similarly, in COVID‐19‐associated pulmonary fibrosis, SLC16A4 may mediate intercellular lactate signaling, activating fibrosis‐related pathways, such as fibroblast proliferation and ECM accumulation." (PMID 41532065, 2026). "In summary, our findings highlight lactate metabolism, particularly via SLC16A4 and PDGFC–PDGFRA signaling, as a potential driver of COVID‐19–associated pulmonary fibrosis and a promising target for future therapeutic intervention." (PMID 41532065, 2026). "Our study shows that COVID‐19 infection upregulates SLC16A4 expression in lung epithelial cells, leading to lactate accumulation, which in turn promotes the progression of pulmonary fibrosis." (PMID 41532065, 2026). "This study reveals that COVID‐19 promotes the development of pulmonary fibrosis through the lactate metabolic pathway regulated by the SLC16A4 gene in lung epithelial cells." (PMID 41532065, 2026). "This study uncovers a critical mechanism by which COVID‐19 promotes pulmonary fibrosis through the regulation of lactate metabolism in lung epithelial cells, with SLC16A4 playing a pivotal role." (PMID 41532065, 2026). "This study highlights the critical role of SLC16A4 in regulating lactate metabolism during COVID‐19 infection and suggests that SLC16A4 may be a potential therapeutic target for preventing or treating lung fibrosis." (PMID 41532065, 2026).
cancer (4 papers, 2015 to 2025). A tumor composed of atypical neoplastic, often pleomorphic cells that invade other tissues. "Additionally, enrichment analysis revealed that SLC16A4 was associated with several cancer-related signaling pathways, including drug metabolism cytochrome P450 (NES = 2.384), cell cycle (NES = −2.706), and mismatch repair (NES = −2.282)." (PMID 40867526, 2025). "Similar findings were observed in the CPTAC LUAD and LUSC datasets, where mRNA expression of SLC16A4 was consistently reduced in cancer tissues." (PMID 40867526, 2025). "Interestingly, elements of Box B are known regulators of apoptosis in various contexts, including the neuronal environment with ENO1 and SLC16A4, and different types of cancer." (PMID 30157777, 2018). "However, studies on SLC16A4, SLC16A10, SLC16A11, SLC16A13, and SLC16A14 in cancer are still lacking." (PMID 34424811, 2021).
tumor (4 papers, 2022 to 2025). "Additionally, correlation analyses revealed that SLC16A4 expression was inversely associated with microsatellite instability (r = −0.291) and tumor mutation burden (r = −0.200)." (PMID 40867526, 2025). "Regarding tumor staging, SLC16A4 expression was significantly lower in early-stage tumors (Stage I-III) compared to late-stage tumors (Stage IV) and normal tissues." (PMID 40867526, 2025). "Further research into the mechanisms of SLC16A4 in cell proliferation, senescence, and immune escape will help elucidate its potential as an anti-tumor target." (PMID 40867526, 2025). "The mRNA expression of seven PRAN genes (CCL14, CPA3, CX3CR1, IKZF3, KIF21B, LINC00528, and SLC16A4) exhibited noticeable difference between normal and tumor in NSCLC." (PMID 38728242, 2024). "The mRNA expression of seven PRAN genes (CCL14, CPA3, CX3CR1, IKZF3, KIF21B, LINC00528, and SLC16A4) showed significant differences between normal and tumor samples in the advanced NSCLC cohort." (PMID 38728242, 2024). "Cells absorb glucose via GLUT1(SLC2A1), hypoxic cells release lactate through MCT4(SLC16A4), while tumor cells and endothelial cells absorb lactate through MCT1(SLC16A1)." (PMID 37795453, 2023). "SLC16A4 expression was found to be significantly negatively correlated with tumor stemness as quantified by RNA-based stemness scores (RNAss) (r = −0.585) and similarly showed a strong negative correlation with the expression of the stemness-associated marker gene SOX2 (r = −0.551)." (PMID 40867526, 2025).
SLC16A4 also shares sentences with these, for which no sentence is quoted: hypothyroidism (1 paper); infection (1); squamous cell carcinoma (1).